NPY (neuropeptide Y)
Diseases named in the same sentence as NPY in open-access papers (continued):
Sharing a sentence is not in itself a finding about the gene and the disease.
Obesity (continued). "Neuropeptide Y (NPY) is a neurotransmitter associated with feeding and obesity." (PMID 23118773, 2012). "However, genetic removal of NPY attenuated hyperphagia and obesity phenotype in leptin-deficient mice." (PMID 23346045, 2012). "In the current study, we hypothesized that NPY overexpression would render the transgenic mice even more susceptible to obesity induced by a Western-type diet." (PMID 23118773, 2012). "Moreover, obese ARC-NPY rats presented high NPY serum levels as compared to controls underlie the contribution of sympathetic NPY to the development of obesity." (PMID 21799827, 2011). "Alterations in the hypothalamic NPY levels are also associated to obesity." (PMID 21799827, 2011). "ARC NPY overexpression causes serum alterations consistent with obesity and elevated serum NPY." (PMID 21799827, 2011). "However, NPY deficiency does lead to attenuated responses to fasting and a high fat diet, and it also attenuates hyperphagia and the obesity syndrome of ob/ob mice." (PMID 20613867, 2010). "Due to its angiogenic properties, NPY has been implicated in various pathological conditions associated with a deregulation of tissue vascularization, such as retinopathy, wound healing, atherosclerosis, and obesity." (PMID 20508839, 2010). "Since SIL has these functions and obesity was associated with hyperlipemia, hormonal disorder, and overexpression of brain NPY, we conducted studies on SIL against weight gain to search whether there was a fundamental mechanism between silymarin-loaded chitosan and the weight loss effect." (PMID 38645495, 2024). "Furthermore, although obesity and infertility are seen in leptin‐deficient ob/ob mice, these phenotypes are ameliorated in NPY‐deficient ob/ob mice, suggesting that NPY functions as a central effector that mediates the effects of leptin on the appetite and reproductive systems." (PMID 34934398, 2022). "The exact pathomechanisms responsible for this connection are not yet completely understood but might involve stress-related neuropeptide Y expression in the central amygdala that may cause insulin resistance, resulting in increased food intake and excessive development of obesity." (PMID 35041124, 2022). "Moreover, SNPs in the NPY have been associated with obesity." (PMID 36532520, 2022). "As obesity-related metabolic abnormalities include not only glucose metabolic disorders but also dyslipidemia and hypertension, our results further support the positive association between NPY and metabolic disturbances reported in the existing research literature." (PMID 32831640, 2020). "Obesity and uremia status may be the maximal expression of this disorder since both are associated with the hyperinsulinemia and insulin resistance that might perpetuate the abnormal NPY release." (PMID 31191339, 2019). "Stress has been linked to obesity via multiple mechanisms: centrally, through its hypothalamic actions on food intake, and peripherally, via direct actions on adipose tissue of sympathetic neurotransmitters, NPY and catecholamines, parasympathetic activity and glucocorticoids." (PMID 22570731, 2012). "Thus, NPY overexpression overrode the resistance of the C57Bl/6 female mice to the diet-induced obesity, but susceptibility of the male C57Bl/6 mice to the diet induced obesity overrode the NPY's adiposity inducing effect." (PMID 23118773, 2012). "Early studies into the modulation of NPY signaling as a means for obesity treatment have demonstrated some promise but there is still much to be done." (PMID 41151834, 2026). "Given the role of NPY in increasing appetite, NPY was thought of as a potential target for obesity therapeutics." (PMID 41151834, 2026). "The interplay between calorie-dense food and chronic stress significantly accelerates obesity development, with neural circuits expressing Neuropeptide Y (NPY) in the central amygdala (CeA) emerging as the key mediator of this process." (PMID 40480630, 2025).
Obesity (continued). "NPY also stimulates one's appetite and reduces fat utilization and energy consumption, leading to fat accumulation and even obesity, which will further aggravate OSAS." (PMID 40989139, 2025). "SCFAs increase the secretion of the incretin hormone glucagon-like peptide (GLP)-1, and inhibit the secretion of neuropeptide Y, which reduces appetite and counteracts obesity." (PMID 41156555, 2025). "NPY showed protective function under some pathological conditions, such as stress, ischemia, obesity and neuroinflammation." (PMID 39905012, 2025). "Previously, high concentrations of obesity-related NPY levels in the hypothalamus were found in the male rats exposed to melatonin (Mel) during the prenatal period, up to 40 days of age." (PMID 40636869, 2025). "However, when malnutrition affects transcription factors, this can lead to delayed recovery, which can contribute to the development of obesity, among other diseases, in the long term, which may be associated with neuropeptide derangement (such as a reduction in NPY) in rats." (PMID 41154756, 2025). "The disorder in NPY expression is one of the neurochemical similarities between obesity and depression." (PMID 40636869, 2025). "Another mechanism of the HPA axis’ involvement in obesity is favouring the expression of orexigenic neuropeptides, i.e., neuropeptide Y (NPY)." (PMID 41375608, 2025). "Considering the anti-obesity property of Mel, it has been suggested in recent years that it reduces the orexigenic effect by reducing NPY/Agouti-related peptide (AgRP) in the hypothalamus." (PMID 40636869, 2025). "These NPY-cKO mice have reduced thermogenic ability and lower energy expenditure, show cold intolerance, develop late-onset obesity on a regular chow diet and rapidly develop obesity when fed a high-fat diet, without eating more." (PMID 39198648, 2024). "Sixty minutes of MICE increased IL‐6 and irisin concentrations while suppressed NPY and appetite perceptions in males with obesity." (PMID 39722170, 2024). "Another example of brain-bone crosstalk is neuropeptide Y (NPY), which is expressed by central and peripheral nervous systems to regulate bone formation in response to obesity and fasting." (PMID 38566930, 2024). "Conditional knockout of NPY (NPY-cKO) in sympathetic neurons depletes mural cells and whitens brown fat before the onset of obesity, rendering this tissue hypertrophic and with reduced thermogenic ability." (PMID 39198648, 2024). "The loss of NPY in sympathetic neurons whitened interscapular BAT, reducing its thermogenic ability and decreasing energy expenditure before the onset of obesity." (PMID 39198648, 2024). "The hormone Neuropeptide Y (NPY) plays critical roles in feeding, satiety, obesity, and weight control." (PMID 38914733, 2024). "Previous studies report that NPY peptide is related to stomach physiological functions, such as appetite regulation and obesity induction." (PMID 39458969, 2024). "We found that diet-induced obesity leads to neuropathy of NPY+ axons and concomitant depletion of mural cells." (PMID 39198648, 2024). "For example, specific ablation of Y2 receptors on NPY neurons led to a marked increase in obesity in female mice." (PMID 37452264, 2023). "As occurs with NPY levels, in patients with obesity, the ratio of acyl/des-acyl ghrelin duplicates in fasting conditions." (PMID 36830982, 2023). "Deletion of the Npy gene attenuates weight gain in mice fed an HF diet, showing the involvement of NPY in obesity development." (PMID 36830982, 2023). "As such, the introduction of omega-3 and omega-9 fatty acids in diet-induced obesity reduced hypothalamic expression of NPY and MCH while increasing expression of POMC and CART in a mouse model." (PMID 37571301, 2023). "Outcomes in NPY over-expressing mice are also consistent with a role for altered SNS activity in NPY-dependent obesity and metabolic syndrome." (PMID 37153459, 2023).
Obesity (continued). "Collectively, our findings indicate that FHL2, as a positive regulator of NPY and MCP-1, is closely linked to the mechanism of obesity-associated lipid accumulation and inflammation in VAT." (PMID 37834391, 2023). "This review focuses on the interconnection between mitochondrial function and dynamics with central and peripheral neuropeptide Y actions and discusses possible therapeutical modulations of the neuropeptide Y system as an anti-obesity tool." (PMID 36830982, 2023). "The knockout of NPY can attenuate obesity and other related symptoms in ob/ob mice, suggesting that NPY plays a role in the response to leptin deficiency." (PMID 37452264, 2023). "We found that HMBA bound to MYH9 and ACTG1, which were required for the anti‐obesity effects of HMBA in both NPY‐expressing and POMC‐expressing neurons." (PMID 37984341, 2023). "There is evidence for an important interaction between SNS and NPY activities in development of obesity and metabolic disease." (PMID 37153459, 2023). "In the PVN region, obesity-prone rats that were inbred showed a reduction in agouti-related protein/NPY processes." (PMID 36899905, 2023). "High fat feeding-induced obesity affects the NPY/AgRP co-expressing neurons in the arcuate nucleus via cytokines that promote hypothalamic inflammation and astrocytosis." (PMID 37571301, 2023). "It is noteworthy that NPY stimulates food intake and inhibits energy expenditure, leading to obesity." (PMID 37149580, 2023). "Recently, strategies targeting the NPY signaling pathway have been explored for obesity and diabetes interventions in animal studies, and some exciting metabolic benefits have been reported." (PMID 37149580, 2023). "The present study disclosed that rWAT denervation blunted the decrease in bone formation observed in HFD-induced obesity rat model possibly through a preferential reduction in the neurohormonal actions of serum and hypothalamic NPY." (PMID 37630764, 2023). "In mice and rats, expression of NPY in the ArcN/PVN is reduced by diet-induced obesity or, in the ArcN, by NPY mRNA levels." (PMID 36899905, 2023). "Obesity renders ArcN NPY and POMC neurons resistant to leptin, including those that influence PVN TRH neurons." (PMID 36769012, 2023). "Given the role of NPY in regulating both arms of the energy balance, it would be an interesting approach to develop a new treatment for obesity mediated by this powerful peptide, although the alterations on the NPY system are still to be fully addressed." (PMID 36830982, 2023). "Collectively, these findings indicate that FHL2 is a positive regulator of NPY and MCP-1 expression in macrophages and herewith closely linked to the mechanism of obesity-associated lipid accumulation and inflammation in VAT." (PMID 37834391, 2023). "The circulatory levels of NPY are reported to be elevated in hypertensive subjects, obesity, preeclampsia, and in some malignancies such as neuroblastoma and Ewing sarcoma due to high neuropeptide synthesis within tumor tissues." (PMID 35121782, 2022). "Acute administration of NPY increases food intake and induces hyperinsulinemia, whereas its chronic administration produces hyperphagia and obesity and decreases thermogenesis." (PMID 35683029, 2022). "Studies have shown that increasing NPY levels in mice lead to hyperglycemia, impaired glucose tolerance, hyperphagia, and obesity." (PMID 35627254, 2022). "The relevance of NPY signaling to skin disease in relationship to adipocytes and obesity is particularly highlighted in psoriasis." (PMID 35418942, 2022). "NPY can also trigger lipogenic enzymes in the adipose tissues, which contributes to obesity development." (PMID 35328389, 2022). "When neuropeptide Y (NPY) was first discovered in 1983, the awareness of its function in energy balance, obesity, and bone metabolism has gradually increased." (PMID 35273572, 2022).
Obesity (continued). "Melatonin has been reported to control energy balance and improve obesity by suppressing appetite-promoting polypeptide (NPY) in patients with osteoporosis." (PMID 36421874, 2022). "Dysfunctions of the NPY system have been observed in diseases such as obesity, type II diabetes and metabolic syndrome." (PMID 35683029, 2022). "POMC (Pro-opiomelanocortin) and NPY (Neuropeptide Y) are two appetite-regulating genes whose methylation is altered in obesity; POMC promotes satiety, while NPY stimulates food intake." (PMID 35163268, 2022). "Copper is an essential component for the cuproenzyme peptidylglycine monooxygenase which is responsible for the α-amidation of NPY, suggesting that the effect of copper on NPY was another likely mechanism by which excessive copper induced obesity." (PMID 36466427, 2022). "While five of these exercised a direct and unique effect on obesity only, both pathologies were jointly affected by the remaining three, namely cortisol, NPY, and OXT." (PMID 35959009, 2022). "Taken together, many animal studies furnish the role of leptin, adiponectin, and NPY in appetite modulation and systematic effects on obesity." (PMID 36064382, 2022). "Unfortunately, cortisol and NPY while mediating reduced severity in PTSD are predicted to concurrently exacerbate obesity." (PMID 35959009, 2022). "Thereby, the reduced NPY signaling and concomitant increased NE signaling in visceral fat decreased the abdominal fat deposition in mutant mice during diet-induced obesity." (PMID 36293486, 2022). "Male mice targeted disruption of the Npy1r gene in limbic areas were used to study the effect of NPY-Y1R system in energy balance and emotional behavior as well as diet-induced obesity." (PMID 36267563, 2022). "Chitosan supplementation can improve cardiometabolic parameters (anthropometric indicators of obesity and lipid and glycemic markers) and appetite-related hormones (adiponectin, leptin, and NPY) in adolescents with overweight or obesity." (PMID 36064382, 2022). "Several studies reported that NPY expression in the DMN is increased in rodents with obesity, and the increased NPY levels play a significant role in the development of diet induced obesity (DIO) as well as the regulation of thermogenesis." (PMID 35721722, 2022). "NPY promotes obesity after binding Y1R and Y2R expressed within white adipose tissue (WAT), which promotes WAT proliferation." (PMID 34344469, 2021). "Short neuropeptide F is a functional homolog of Neuropeptide Y, a strong orexigenic peptide that promotes diet-induced obesity in mammals." (PMID 34803746, 2021). "NPY is elevated in obesity and promotes energy storage, and decreases in response to administration of leptin or insulin." (PMID 33716966, 2021). "In adults, however, excessive NPY signaling leads to obesity and NPY increases adipocyte size in hyperinsulinemic conditions." (PMID 34572017, 2021). "The diet-induced obesity suppressed the neuroendocrine ghrelin system by decreasing ghrelin production in the stomach, as well as by ghrelin resistance in arcuate NPY/AgRP neurons." (PMID 34445772, 2021). "Although NPY is an orexigenic peptide, Y1 and Y5 receptor deletion leads to obesity and decreases food intake." (PMID 34445614, 2021). "Studies report that repeated intracerebroventricular (ICV) injection of NPY leads to hyperphagia and obesity." (PMID 33868169, 2021). "Injection of NPY into either the cerebral ventricles or the hypothalamus stimulates food intake even in satiated rats, eventually leading to obesity." (PMID 34445453, 2021). "NPY neuron-specific LepR knockout mice develop obesity and diabetes, which is similar to that of db/db (LepR deficient mice) mice." (PMID 34307371, 2021). "The results suggested that deficiency of Mir342 links to the reduced population and blunted activation of NPY orexigenic neurons, which result in reduced food intake and amelioration of obesity and diabetes under HFHS chow." (PMID 34526970, 2021).
Obesity (continued). "When all rats were fed a high-energy diet for 14 weeks, NPY mRNA expression was reduced dramatically in obesity-prone rats and remained well below the level of obesity-resistant rats, made similarly obese on a highly palatable diet." (PMID 34199898, 2021). "The fasting serum levels of neuropeptide Y were decreased in adolescent patients with anorexia nervosa, as well as in those with obesity." (PMID 33670342, 2021). "NPY promotes energy storage in white adipose tissue; knockout of NPY in the hypothalamus promotes thermogenesis and energy expenditure and prevents obesity." (PMID 34468315, 2021). "The role of hypothalamic Y1R in mediating NPY-induced hyperphagia has been an early focus in obesity research." (PMID 34445453, 2021). "When both obesity-prone and obesity-resistant rats were fed a standard chow diet, obesity-prone rats had 59% higher neuropeptide Y (NPY) mRNA expression in the hypothalamus, a known stimulator of food intake, than obesity-resistant rats." (PMID 34199898, 2021). "Nonetheless, obese patients usually display reduced circulating PYY and PP as well as elevated NPY levels which suggests a role of the PP-fold family in the pathophysiology of obesity." (PMID 34680059, 2021). "Neuropeptide Y neurons play critical role in metabolic diseases, including obesity, glucose tolerance, hypertension and atherosclerosis." (PMID 34307371, 2021). "NPY expression in the hypothalamic arcuate nucleus is increased in obesity, which inhibits the SNS through the neuroendocrine route, where it co-exist with norepinephrine." (PMID 34829968, 2021). "Very recent evidence has documented that suppression of insulin signaling on CeA NPY neurons is a major mechanism for the development of hyperphagia and obesity in a mouse model of HFD and chronic stress." (PMID 34940594, 2021). "Obesity and its related metabolic abnormalities are closely related to dietary intake and the resulting energy imbalance, which is largely regulated by NPY." (PMID 32831640, 2020). "Collectively, these data highlight the role of the ArcN, specifically POMC and NPY neurons, as a site of sexual dimorphism in obesity-induced sympathoexcitation in OP versus OR/control males and females." (PMID 32160920, 2020). "In adult mice, diet-induced obesity suppresses GABAergic and glutamatergic tone to NPY neurons, whereas fasting increases excitatory transmission to NPY-expressing cells." (PMID 32823489, 2020). "Neuropeptide Y (NPY) levels were affected by the interaction of both factors, sex and obesity (p = 0.0411)." (PMID 33644105, 2020). "Another study reported that intracerebroventricular administration of neuropeptide Y to normal rats induces a syndrome characterized by obesity, hyperinsulinemia, insulin resistance, and overexpression of the adipose tissue ob gene." (PMID 33415147, 2020). "This does not appear to be due to a decrease in the expression of InsR in NPY neurons; therefore, obesity in females somehow attenuates insulin signaling specifically in presympathetic ArcN neurons." (PMID 32160920, 2020). "Instead, obesity eliminates tonic NPY inhibitory inputs to the PVN in males, allowing excitatory inputs, like α-MSH, to increase SNA, unfettered by inhibition." (PMID 32160920, 2020). "Diet-induced obesity and T2DM have been associated with a disturbed balance between the anorexigenic POMC and the orexigenic NPY/AgRP neurons." (PMID 32814716, 2020). "Neuropeptide Y (NPY), an orexigenic peptide known to cause hyperphagia, has been involved in the occurrence and development of obesity." (PMID 32831640, 2020). "Many obesity models were characterized by an increase in central nervous system NPY tone, which lead to overeating and obesity." (PMID 32831640, 2020). "The highlight of the present study was the stratification of obesity based on its related metabolic disorders in the analysis of NPY levels in obese participants." (PMID 32831640, 2020).